LDHA (lactate dehydrogenase A)
Diseases named in the same sentence as LDHA in open-access papers (continued):
Sharing a sentence is not in itself a finding about the gene and the disease.
glioma (continued). "There have been a few studies of LDHA and lactate in high‐grade glioma migration." (PMID 26269128, 2016). "In this study, we investigated the expression and function of LDHA in glioma." (PMID 27374173, 2016). "LDHA expression is silenced by hypermethylation in patient-derived mutant IDH1 glioma models." (PMID 27144334, 2016). "Firstly, LDHA was found to be up-regulated in glioma cell lines and samples." (PMID 27374173, 2016). "The results showed that LDHA was up-regulated in glioma compared to normal samples." (PMID 27374173, 2016). "Furthermore, we found that overexpression of LDHA promoted proliferation, invasion and glycolysis in glioma cells." (PMID 27374173, 2016). "Our findings may provide significant evidence regarding miR-200b as an important tumor suppressor in glioma through targeting LDHA." (PMID 27374173, 2016). "LDHA is involved in substania nigra development and is deregulated in glioma tumors." (PMID 26085845, 2014). "Finally, our data suggest that the detected metabolic heterogeneity (the high mTORC2 complex activity, enhanced expression of Rictor, p-Akt, p-S6, CPT1A, and LDHA enzymes in glioma cases) and the microenvironmental or treatment induced metabolic shift can be potential targets in combination therapy." (PMID 31187466, 2020). "We also observed that silencing of circPOSTN could inhibit HK2 and LDHA expression in glioma cells." (PMID 32774168, 2020). "Inhibiting LDHA through miR-200b could be a promising strategy in treating glioma." (PMID 27374173, 2016). "Targeting LDHA through miR-200b could be a potential therapeutic strategy in glioma." (PMID 27374173, 2016). "However, LDHA expression is typically silenced in mutant IDH1 gliomas, suggesting that pyruvate conversion to lactate could be reduced." (PMID 27144334, 2016). "As LDHA has previously been shown to be important in tumor growth and progression in many other tumors, the silencing of LDHA in gliomas with IDH mutations may be responsible in part for the characteristically slow progression of gliomas with IDH mutations." (PMID 26269128, 2016). "Additionally, LDHA expression is stronger in GBMs than in other grades of gliomas." (PMID 23456655, 2013). "Here, we identify SMC4 as a multifunctional oncoprotein driving glioma progression through dual mechanisms: activation of TGF-β/Smad-mediated metastasis and LDHA-dependent metabolic reprogramming." (PMID 40933894, 2025). "Inspired by this, a glucose metabolism‐related gene (GMG)‐based model, including LDHA, GUSB, GLB1, GALM, and FBP1, was proposed based on protein‒protein interaction analysis to predict the prognosis of patients with glioma." (PMID 39830021, 2025). "Studies have demonstrated that LDHA and MCT1 are overexpressed in glioma and are positively correlated with the infiltration of CD163+/CD206+ M2-type GAM." (PMID 41463052, 2025). "SMC4 drives glioma progression through dual mechanisms TGF-β/SMAD-mediated metastasis and LDHA-dependent glycolysis regulated by NFIA." (PMID 40933894, 2025). "The immunohistochemical images of LDHA and SLC16A1 in normal cerebral cortical and glioma tissues were retrieved from the HPA database." (PMID 40782248, 2025). "Consistent with the changes in expression, patients with higher expression of LDHA, MIF, NAMPT, PGK1, SAT1, and PLOD2, and lower expression of ALDOC, ABAT, ADCY2, GALNT13, and PDE8B showed poorer survival rates in all glioma samples." (PMID 38989284, 2024). "Elevated expressions of LDHA and MCT1 were observed in glioma and exhibited a positive correlation with M2-type TAM infiltration." (PMID 38576043, 2024). "Hypoxic wt-IDH glioma tissues from patients show a glycolytic phenotype due to the upregulation of PGK1, PKM2, LDHA, SLC16A3, and CA9 via HIF1." (PMID 38786726, 2024). "IDH mutant glioma tissue and brain tumor stem cells derived from IDH1 mutant glioma tissue show reduced expression of lactate dehydrogenase A (LDHA), the enzyme responsible for converting pyruvate into lactate." (PMID 39596840, 2024).
glioma (continued). "Our research indicated that oxidative stress triggered the entry of LDHA into the nucleus, which manipulated BCAA metabolism to acquire supplementary glutamate for the synthesis of the antioxidant TxN to sustain glioma cell proliferation." (PMID 37298317, 2023). "In CGGA (Chinese Glioma Genome Atlas), a significant positive correlation was found between LDHA and BCAT1 expression in both primary and recurrent gliomas, and a similar positive correlation was observed in gliomas at all malignant levels." (PMID 37298317, 2023). "We also assessed LDHA and MCT4 levels in glioma samples from The Cancer Genome Atlas (TCGA), including 524 cases of low-grade gliomas (LGG) and 167 cases of high-grade gliomas (HGG)." (PMID 35864093, 2022). "The same tendency was observed when the expression of LDHA and LDHB was analyzed in low‐grade gliomas." (PMID 36278433, 2022). "Extending these findings from clinical data to animal models, our IHC analysis of the brains of healthy and U251 tumor-bearing mice showed that the LDHA and MCT4 levels were significantly higher in the glioma brains than in normal brains." (PMID 35864093, 2022). "Enhanced LDHA expression, as observed in IDH wild-type glioma, in rapidly growing cells and under hypoxic conditions, promotes angiogenesis." (PMID 34439213, 2021). "ANXA2P2 is up-regulated in glioma cells, and it modulates the aerobic glycolysis and proliferation of glioma cells through ANXA2P2/miR-9/LDHA axis." (PMID 34819492, 2021). "The results showed that expression levels of VEGFA, HK2, JUN, LDHA, and GAPDH were significantly high in glioma with wildtype-IDH and wildtype-1p/19q codeletion." (PMID 32500034, 2020). "The activity of LDHA assessed by hyperpolarized-MRSI utilizing 13C-1-pyruvate has been proposed as a biomarker of response to treatment and aggressiveness in gliomas." (PMID 32575619, 2020). "In the top 5 of differentially expressed genes were LDHA and BCAT1, genes that are known to be hypermethylated in low grade, IDHmut gliomas." (PMID 31747973, 2019). "Chesnelong and colleagues reported that HIF 1α responsive, glycolysis-related genes such as SLC2A1, PDK1, LDHA and SLC16A3 are under-expressed in IDH mutant gliomas." (PMID 29439493, 2018). "IDH-mutant human gliomas also have reduced levels of hypoxia-inducible factor (HIF) 1α and the glycolytic enzyme lactate dehydrogenase A (LDHA)." (PMID 25785247, 2015). "Such mechanistic clarity will not only refine our understanding of metabolic–epigenetic–immune crosstalk but also support the rational development of therapies such as LDHA or MCT inhibition in combination with immunotherapy—particularly in lactate-high, immune-cold glioma subtypes." (PMID 41463052, 2025). "The protein levels of LDHA and SLC16A1 were analyzed using the Human Protein Atlas (HPA) database, and the differential expression and function of LDHA and SLC16A1 were validated in glioma cell lines." (PMID 40782248, 2025). "Consistent with the bioinformatics analysis, the results indicated increased protein expressions of LDHA and MCT1 in gliomas compared to peri-tumorous normal tissues (Peri-NT), with notably higher levels in glioblastomas (GBM) compared to low-grade gliomas (LGG)." (PMID 38576043, 2024). "Moreover, the analysis in TCGA database consistently demonstrated a positive correlation on LDHA and CD39 expressions in glioma patients." (PMID 37770937, 2023). "We detected a clear trend: the Ki67, LDHA, and MCT4 levels were increased from grade II to grade III and gained to grade IV, and there was a positive correlation between the levels of above LA metabolic indicators and the extent of glioma proliferation." (PMID 35864093, 2022).
glioma (continued). "Moreover, IDH1 wild-type gliomas displayed a significantly increased expression of glycolytic enzyme genes (LDHA, HK2, PGAM2, PGK1, PKM, TIGAR) compared to IDH1-mutant gliomas as shown in heatmaps." (PMID 33493139, 2021). "LDHA knockdown impeded glucose uptake and lactate production, whereas the rescue expression of LDHA WT, but not LDHA Y10F mutant, restored the glucose uptake and lactate production in glioma cells." (PMID 34452627, 2021). "In glioma cells, overexpression of c-Myc, a WNT target gene, promotes the Warburg effect via activation of downstream genes, such as glucose transporter (Glut), hexokinase (HK), pyruvate dehydrogenase kinase 1 (PDK1), and lactate dehydrogenase A (LDH-A)." (PMID 28620312, 2017). "Reduced MCT expression in IDH1MUT glioma is consistent with reduced glycolytic production of lactate as well as silencing of LDHA expression; cells that produce less lactate do not require an increase in its export and are less dependent on MCT expression." (PMID 28467784, 2017). "Our finding regarding reduced expression of the MCTs, taken together with reduced intracellular lactate levels and the silencing of LDHA expression, indicate that in mutant IDH1 gliomas in vivo the production of hyperpolarized lactate is likely to be very limited." (PMID 27144334, 2016). "Conversely, while LDHA demonstrates robust antitumor potency in glioma models, the absence of formal human trials currently designates it as a medium-to-long-term ‘high-risk, high-reward’ target, requiring validation of safety and efficacy through rigorously designed early-phase exploratory studies." (PMID 41463052, 2025). "Results indicated a marked upregulation of LDHA at both mRNA and protein levels in LN229 and U87MG cells, whereas LDHB was significantly expressed in U251MG and SW1783 cells at both mRNA and protein levels, highlighting differential LDH subunit expression across these glioma cell lines." (PMID 39895794, 2025). "The differential expression of the LDHA protein, a key glycolytic enzyme, in different molecular phenotypes of IDH1 may lead to heterogeneity in glycolytic energy metabolism in glioma cells and may affect glioma cell migration, invasion, and proliferation." (PMID 37066523, 2023). "Lactate dehydrogenase A (LDHA), as the key element of converting pyruvate to lactate, overexpressed in tumor cells could also contribute to the regulation of TGF-β and the rise of MMP-2 in glioma cells." (PMID 37328876, 2023). "However, it has yet to be studied whether LDHA also enters the nucleus, facilitating BCAA metabolism under oxidative stress in glioma cells." (PMID 37298317, 2023). "Our study showed that LDHA, MRS2, and SLC16A1 were indicators of poor survival, while LDHB and SLC25A12 were indicators of favorable prognosis, suggesting that lactate metabolism is dysregulated in glioma and this dysregulated expression is closely related to tumor progression." (PMID 36698888, 2022). "LDHA, which catalyzes oxidation of pyruvate to lactate, is downregulated in mutIDH1R132H glioma cells, PDX (mouse), and PTBs,213,217,218 whereas LDHB (which converts lactate to pyruvate) has increased expression in mutIDH1R132H-expressing BT142 cells, PTBs, and PDX (mouse) gliomas." (PMID 35028610, 2021). "Our data indicated that AS of GLS and LDHA were signatures of pST6 and pST7, respectively, the clusters with the best prognosis, suggesting that both expression and AS of metabolic enzymes might be involved in IDH-mutant glioma." (PMID 31729991, 2019). "Moreover, we analyzed the correlation between the level of LDHA and miR-200b in 73 glioma samples, and detected a negative correlation between them." (PMID 27374173, 2016). "The expression levels of EMB, LDHA, SLC16A1, SLC16A3, SLC16A8, PARK7, and PFKFB2 were lower in 1p/19q Codel glioma than those in non-Codel glioma." (PMID 36698888, 2022).
gastric cancer (79 papers, 2014 to 2025). A primary or metastatic malignant neoplasm involving the stomach. "Recently, high succinylation of LDHA at K222, which inhibits LDHA degradation, has been observed and reported to be associated with poor prognosis in gastric cancer patients." (PMID 35090076, 2022). "Thus, the level of succinylated LDHA is positively associated with poor prognosis in patients with gastric cancer." (PMID 37777749, 2023). "Blood samples were collected from gastric cancer patients with stage I (n = 15), II (n = 15), III (n = 15) and IV (n = 15) disease for enzyme-linked immunosorbent assays to investigate whether LDHA affects gastric cancer development and progression." (PMID 38041125, 2023). "Besides, high ZEB2 expression was strongly associated with lactate dehydrogenase A (LDHA) expression in gastric cancer, and LDHA was a crucial enzyme in the final step of the Warburg effect, through which high rate of glycolysis was executed in cancer cells." (PMID 28416756, 2017). "For instance, the hypoxia-induced FOXO4/LDHA axis was found to play a pivotal role in regulating glycolysis and tumor progression in gastric cancer." (PMID 40149900, 2025). "Carnitine palmitoyltransferase 1A (CPT1A), by influencing LDHA at K222, increases its succinylation level, inhibiting LDHA degradation, thus enhancing glycolysis and promoting the invasion and proliferation of gastric cancer." (PMID 39781339, 2025). "SIRT3 can interact with another subunit of LDHA and deacetylate it, enhancing LDHA activity and promoting glycolysis and gastric cancer cell proliferation." (PMID 39778006, 2025). "In gastric cancer, the upregulation of lactate dehydrogenase A (LDHA), a critical enzyme in lactate production, has been associated with resistance to neoadjuvant chemotherapy." (PMID 40717080, 2025). "Abnormal LDHA accumulation promotes the Warburg effect in cancer cells, and overexpression also disturbs the regulation of matrix proteins, influencing gastric cancer development and progression." (PMID 40865948, 2025). "H19 is overexpressed in gastric cancer (GC) cells and contributes to immune escape from GC cells by decreasing immune cell activity and IL-2 expression through the miR-519d-3p/LDHA/lactate axis." (PMID 38715092, 2024). "RT‐PCR and western blot results showed that, compared to the SI‐NC group, the upregulation of glycolysis‐related genes PKM2, GLUTA, HK2, and LDHA in gastric cancer cells was reversed in the si‐MALAT1 groups." (PMID 38639382, 2024). "QRT‐PCR and western blot results showed that, consistent with M2‐CM, M2‐EX treatment also led to the upregulation of glycolysis‐related genes PKM2, GLUTA, HK2, and LDHA in gastric cancer cells." (PMID 38639382, 2024). "QRT‐PCR and western blot results showed that M2‐CM induced the expression of several glycolysis‐related genes including PKM2, GLUTA, HK2, and LDHA in gastric cancer cells." (PMID 38639382, 2024). "In gastric cancer cells, H19 inhibits glucose consumption primarily via the H19/miR-519d-3p/LDHA axis, promotes aerobic glycolysis, proliferation, and regulates immune cell activity, including T cells, Jurkat cells, and TAMs." (PMID 38523627, 2024). "We found that in the presence of β‐catenin inhibitor ICG001 and HIF‐1α inhibitor PX‐478, the upregulation of glycolysis‐related genes PKM2, GLUTA, HK2, and LDHA in gastric cancer cells by M2‐EX was greatly attenuated." (PMID 38639382, 2024). "H19 has been shown to promote aerobic glycolysis, cell proliferation, and immune escape in gastric cancer cells by acting through the miR-519d-3p/LDHA axis." (PMID 38744310, 2024). "Our single cell data analysis also showed GLUT3 and LDHA enrichment in a variety of immune cells, such as Tregs and macrophages, in gastric cancer." (PMID 38041125, 2023). "Wogonin treatment inhibits the action of LDHA in human gastric cancer and lung adenocarcinoma cells." (PMID 37892405, 2023).
gastric cancer (continued). "Immunohistochemistry results showed that the levels of LDHA and L-lactyl were significantly higher in gastric cancer tissues than in normal gastric tissues." (PMID 38041125, 2023). "These in vitro results demonstrate that GLUT3 affects gastric cancer cell metastasis and invasiveness by regulating LDHA." (PMID 38041125, 2023). "Western blotting showed that GLUT3 and LDHA levels were lower in normal gastric mucosal epithelial cells (GES-1) than in gastric cancer cell lines (AGS, HGC-27, KATO III, MKN-1, and MKN-45)." (PMID 38041125, 2023). "Succinylation of LDAH at K222 affects the degradation of LDHA by binding to SQSTM1 in lysosomes, and the increased LDHA contributes to the proliferation and invasion of gastric cancer cells." (PMID 37777749, 2023). "LDHA, an enzyme controlling lactate production and the Warburg effect, is highy succinylated at K222 in gastric cancers that prevents K63-ubiquitinated LDHA from interacting with sequestosome 1 (SQSTM1) and thus reduces its lysosomal degradation." (PMID 36605449, 2022). "Consistently, expressions of glycolysis key enzymes, GLUT1, hexokinase 2 (HK2), and lactate dehydrogenase-A (LDHA) were significantly upregulated in 5-Fu-resistant gastric cancer cells." (PMID 36447254, 2022). "Catechin, one of the flavonoids found in green tea, has been shown to inhibit LDHA activity, which was over-expressed in 5FU-resistant gastric cancer SNU620 cells, resulting in increased sensitivity to 5FU and apoptosis induced by ROS." (PMID 36339566, 2022). "FOX4 is down-regulated in gastric cancer cells, and reduces LDHA viability, resulting in enhanced active glycolysis in gastric cancer cells." (PMID 36438836, 2022). "CircSMARCA5 promotes the expression and activity of LDHA and lactate production of tumor cells in prostate cancer, while it inhibits the uptake of glucose and glycolysis in liver cancer and gastric cancer." (PMID 36231036, 2022). "Further investigation demonstrates that FOXM1 bound to the promoter of LDHA and promotes its transcription in pancreatic and gastric cancer to influence the glycolytic state of cancer." (PMID 36407005, 2022). "The expression of FOX1 is high in gastric cancer cells and promotes glycolysis by increasing the activity of LDHA." (PMID 36438836, 2022). "Proteomics analysis suggests LDHA is upregulated in gastric cancer tissues and highly succinylated on K222." (PMID 36407005, 2022). "CPT1A succinylates LDHA at K222 and impairs the interaction of K63-ubiquitinated LDHA with p62, which inhibiting LDHA degradation and potentiating invasion of gastric cancer cells." (PMID 36202787, 2022). "After treatment with HLE, the phosphorylation of PI3K, Akt, mTOR, and P70S6K was inhibited, and the levels of c-Myc, PDH kinase 1 (PDHK1), and LDHA decreased markedly in MGC803 gastric cancer cells." (PMID 36438836, 2022). "MiR‐34a re-sensitizes colon cancer cells to 5-FU, miR-329-3p sensitizes osteosarcoma cells to cisplatin, and miR-7 sensitizes gastric cancer cells to cisplatin all via LDHA inhibition." (PMID 34540667, 2021). "Total LDHA expression has shown potential as a prognostic marker in some cancers such as clear cell renal cell carcinoma and gastric cancer." (PMID 33996536, 2021). "LDHA is significantly related to octamer-binding transcription factor 4, which plays a key role in the self-renewal of embryonic stem cells in gastric cancer." (PMID 34540667, 2021). "Catechin increases mitochondrial ROS, enhances apoptotic cell death, and reduces 5-FU resistance in gastric cancer via LDHA inhibition." (PMID 34540667, 2021). "SNU620/5FU, a gastric cancer cell harboring resistance to 5FU, showed much higher lactate production and expression of glycolysis-related enzymes, such as lactate dehydrogenase A (LDHA), than those of the parent SNU620 cells." (PMID 34065602, 2021). "In gastric cancer, LDHA was upregulated in tumor tissues and promoted tumor cell migration and invasion." (PMID 32197468, 2020).